SULF2 (sulfatase 2)
Diseases named in the same sentence as SULF2 in open-access papers (continued):
Sharing a sentence is not in itself a finding about the gene and the disease.
adenocarcinoma (1 paper, 2016). A common cancer characterized by the presence of malignant glandular cells. "Importantly, high expression of SULF2 was associated with worse prognosis in patients with adenocarcinoma." (PMID 26882224, 2016). "Nonetheless, these findings are very encouraging, and it seems that the majority of adenocarcinomas samples (including early stage disease), and all of the squamous cell carcinoma tumor samples have some degree of staining for SULF2 protein." (PMID 26882224, 2016).
bacterial infection (1 paper, 2022). "We identified five genes—S100PBP, AKAP1, USP6NL, CDON and SULF2—in five different patient subgroups that have been associated with viral and/or bacterial infection in the literature." (PMID 36517845, 2022).
hematologic malignancies (1 paper, 2014). "Association of heparanase, Sulf1, and Sulf2 in solid tumors and hematologic malignancies." (PMID 25105093, 2014).
renal disease (1 paper, 2022). "The HCC TME, in which we report frequent upregulation of CAF-SULF2, is characterized by activation of the TGFβ1 signalling pathway known to induce SULF2 in renal disease." (PMID 36589727, 2022).
SULF2 also shares sentences with these, for which no sentence is quoted: glioblastoma (2 papers); infection (2); achondrogenesis type IB (1); anaplastic astrocytoma (1); arteriovenous malformations (1); atelosteogenesis type II (1); cardiovascular diseases (1); chondrodysplasia (1); clear cell renal carcinoma (1); ductal carcinoma in situ (1); Failure to thrive (1); Hepatitis (1); Hyperbilirubinemia (1); liver cirrhosis (1); lung diseases (1); muscular disorders (1); neuromyelitis optica (1); Obesity (1); Sjögren’s syndrome (1); systemic lupus erythematosus (1); testicular teratoma (1); triple-negative breast carcinoma (1); uveal melanoma (1).